IL6 (interleukin 6)
Diseases named in the same sentence as IL6 in open-access papers (continued):
Sharing a sentence is not in itself a finding about the gene and the disease.
tumor (continued). "The high concentration of IL-6 compared to healthy individuals has been detected in vitreous humour of UM patients, where it has been positively correlated with the tumour size, infiltration of T cells, and macrophages and disease progression." (PMID 34283046, 2021). "The studies performed on several tumor models have demonstrated that the upregulation of PD-L1 is regulated by the IL-6/STAT3 signaling pathway." (PMID 34829995, 2021). "Inter-cellular pro-tumor activities of IL-6 mainly concern mutant genes in charge of cell cycle, apoptosis and those proto-oncogenes and anti-oncogenes." (PMID 33390844, 2021). "Local and systemic overexpression of IL-6 has been reported in several cancer types, including breast cancer." (PMID 34764420, 2021). "c-Met signaling has been shown to remodel tumor vasculature and induce the production of IL-6 and IL-8." (PMID 34200459, 2021). "Although HIFU does not appreciably activate an adaptive immune response, it induced inflammation via upregulation of Il1β and Il6, which leads to recruitment of MDSCs and subsequent tumor regrowth." (PMID 33441763, 2021). "Based on the observation that IL6 mRNA level was also higher in MC3T3-E1 preosteoclasts co-cultured with KLF5KQ-expressing tumor cells, we confirmed by ELISA that secretion of IL-6 protein was indeed increased in the media of co-cultures." (PMID 33731701, 2021). "Increased inflammatory cytokines such as NF-KB, TNF-α, IL10, IL8, IL6, and increased levels of E. cadherin on epithelial cells activates B-catenin signaling, increases NF-κB, C-myc expression and proliferates tumor cells." (PMID 33823861, 2021). "In the TME, the presence of CAFs and their secretion of chemokines and cytokines such as CCL2, CCL5, CCL17, IL-1, IL-6, IL-13, and IL-26 can favor a tumor-promoting Th2 and Th17 immune response, at the expense of tumor-protective Th1 responses." (PMID 34663337, 2021). "The spatial intratumoral heterogeneity of both IL6 and BCL3 expression was evaluated, corroborating IL6 upregulation throughout the tumor, while tumor and NTST showed a consistent increase of BCL3 expression relative to the healthy esophagus." (PMID 34422669, 2021). "Similar to TNFα, IL‐6 is another important and abundant proinflammatory cytokine in the tumor microenvironment." (PMID 34977871, 2021). "Our results showed that IL6 mRNA and protein expression is upregulated in tumor cells relative to NTST." (PMID 34422669, 2021). "EVs derived from NB cell lines have been demonstrated to affect BM-MSCs: they stimulated the secretion of tumor-supportive cytokines and chemokines from BM-MSCs in vitro, most notably IL-6, IL-8/CXCL8, vascular endothelial growth factor (VEGF), and CCL2/MCP-1." (PMID 33287630, 2021). "Increasing evidence suggested that IL-6 plays an important role to drive tumor progression in several tumor types." (PMID 34657635, 2021). "DESeq2 was used to identify differentially expressed genes in the tumor and stroma of IL-6 KO mice relative to wild-type, and rank list genes by t-statistic." (PMID 34711820, 2021). "Since IL-27 can induce PD-L1 expression in different tumor cell types, we assessed IL-27’s capability of upregulating PD-L1 expression in human MM cell lines as compared to the sIL-6R/IL-6 chimera." (PMID 34439164, 2021). "The phosphorylation and nuclear localization of NF-κB interact with IL-6 and contribute to angiogenesis and invasiveness in tumor progression, which can be reversed by G-1." (PMID 34098945, 2021). "It demonstrated that granulocyte-macrophage colony stimulating factor (GM-CSF) provided the most durable and specific anti-tumour immunity compared to other immunomodulatory cytokines (e.g., IL-2, IL-4, IL-6 and IFN-γ)." (PMID 34944851, 2021). "According to whole-genome transcriptome profiling, certain cytokines and ECM proteins have similar regulatory roles in both tumor growth and wound healing—namely, IL-6, IL-8, chemokine (C-X-C domain) ligand 1, galectin-1, and fibronectin." (PMID 34681685, 2021).
tumor (continued). "Tumor-induced inflammation such as IL-6 has been reported to play a critical role in nutrition metabolism and enhanced body-weight loss in cancer patients." (PMID 34578883, 2021). "An inflammatory cytokine that is of crucial importance in this respect is interleukin 6 (IL-6), which is significantly increased in aggressive tumor microenvironments." (PMID 35582006, 2021). "Specific inducible deletion of IL-6 in ECs strongly decreases M2 macrophage population and slightly increases M1 population, decreases tumor growth, and enhances mice survival." (PMID 33783686, 2021). "In vivo treatment of naringin decreased TNF-α and IL-6 levels, suppressed tumor growth, and increased the survival rate in Wistar rats bearing W256 carcinosarcoma cells." (PMID 33854437, 2021). "In the present study, we found that treatment of highly metastatic tumor-conditioned medium induced resistance to 5-fluorouracil (5-FU) with interleukin-6 (IL-6) upregulation in endothelial cells (ECs)." (PMID 34226586, 2021). "IL-6 is another product of iCAFs that supports tumor growth through multiple mechanisms, including gemcitabine resistance, increased cancer cell invasion and proliferation, and establishment of a metastatic niche in the hepatic parenchyma." (PMID 34948209, 2021). "In response to tumor-derived factors (TGF-β, LPA, IL-1, IL-6) or tumor-derived exosomes, which activate the SMAD, JAK-STAT and NF-κB pathways, fibroblasts become activated." (PMID 33718235, 2021). "M1 macrophages secrete IL-6 and IL-12 to mitigate resistance during tumor development; they can also be activated by IFN-γ to secrete TNF to kill cancer cells, while M2 macrophages secrete growth factors that promote neoangiogenesis and tumor proliferation." (PMID 34447376, 2021). "Once in contact with OS cells, MSCs trans-differentiate into cancer-associated fibroblasts, which, in turn, release cytokines such as IL-6 and IL-8 in the tumor microenvironment, which promote OS cell motility, invasiveness, and trans-endothelial migration." (PMID 34359840, 2021). "IL-6 that is produced by TAM also promotes tumor cells proliferation and invasive potential via STAT3 signaling." (PMID 33418996, 2021). "Clinically, NSCLC patients with increased intratumoral Rab37+IL-6+ immune cells where enriched with tumor infiltrated CD163+ M2-TAMs and exhausted PD-1+CD8+ T cells show poor prognosis." (PMID 34093869, 2021). "IL-6 and IL-8 have been shown to promote a process referred to as “tumor self-seeding”, where CTCs are recruited back to the primary tumor where they modify progression and metastatic fate of cancer cells." (PMID 34064859, 2021). "As the main finding of the protein–protein interaction analysis, IL6 was identified to be an important hub node in the comparison between tumor and normal samples." (PMID 33462316, 2021). "There were studies showing that tumour exosomes promoted the production of IL‐6 and inhibited the differentiation of the CD11b+ myeloid progenitor cells into dendritic cells and macrophages in bone marrow, thus promoting tumour growth." (PMID 33955151, 2021). "IL-6 is considered one of the central players in tumor initiation, tumor growth, and metastasis by regulating fundamental processes like apoptosis, survival, proliferation, and angiogenesis." (PMID 34671021, 2021). "IL-6 plays a significant role in inducing tumor growth as it interacts with the receptor, JAK, to induce STAT-3 activation." (PMID 34307156, 2021). "Consistently, activation of AhR/IL-6/STAT3/ NF-kB signaling was observed in TDO2 overexpression tumor tissues." (PMID 34657635, 2021). "CAFs facilitate tumor development by direct mechanism or indirect mechanism via secreting cytokines and growth factors, such as IL-6, TGF-β6, SDF-1, and also exosome." (PMID 34552063, 2021). "IL-6 and STAT3 in TME are linked with angiogenesis that is the step for tumor migration and metastasis." (PMID 34112144, 2021).
tumor (continued). "MSCs release high levels of cytokines and angiogenesis-stimulating growth factors, including VEGF, βFGF, FGF-2, PDGF, IL-8, IL-6, angiopoietin and TGFβ, which promote tumor angiogenesis." (PMID 33472580, 2021). "IL-6 has been shown to be increased in the tumor tissue and serum of patients with CRC and is correlated with lower patient survival." (PMID 34299049, 2021). "In patients with malignant tumors, CRP levels are reportedly modulated by cytokines, particularly interleukin 6, which is produced by the tumor cells themselves or by the surrounding cells." (PMID 34149913, 2021). "IL-6 and IL-8 can be produced by malignant oral keratinocytes themselves, or by other cells of the TME, such as tumor-associated macrophages (TAMs)." (PMID 35047997, 2021). "IL-23 is present in the tumor microenvironment and triggers the production of IL-17 during Th17 differentiation in synergy with IL-6." (PMID 33498483, 2021). "IL-6 expressed by tumor cells, both in mouse models and in CRC patients, is critical in modeling immune responses in cancer, as well as inducing strong immunosuppression in the CRC microenvironment." (PMID 33557173, 2021). "Tumor-bearing mice had significantly higher IL-6 levels and lower IFN-γ levels compared with the normal mice." (PMID 33854585, 2021). "MSCs are able to release a large number of cytokines to exert their tumor regulatory effects, such as interleukin-6 (IL-6), insulin-like growth factor 1 (IGF-1) or vascular epidermal growth factor (VEGF)." (PMID 34095151, 2021). "Blockade of IL-6 signaling or TNF-α has already been shown to be effective in reducing tumor growth and metastasis in preclinical studies using PDAC mouse models as well as in the therapy of other tumor entities and inflammatory diseases." (PMID 34064969, 2021). "It has been reported that IL-6 serves as a driver of tumor progression, as well as a biomarker of cancer diagnosis and prognosis." (PMID 34001144, 2021). "The serum of tumor-bearing mice after local chest irradiation was detected, and the serum IL-6 level was significantly increased 6 hours after irradiation." (PMID 33854585, 2021). "Experimental studies suggested that inhibition of leptin or IL-6-JAK/STAT3 signaling in CRPC-cells enhances the anti-tumor NKCC via alteration of PD-L1/NKG2D-ligands levels." (PMID 34830209, 2021). "VEGF was used to assess angiogenesis, whereas TGF-β and IL-6 can serve as tumor promoters that induce VEGF to regulate prostate growth, and promote Th2 cell-mediated humoral immunity." (PMID 34604038, 2021). "It was indicated that the invasive properties and proliferation of CSCs are promoted by these cytokines, and that IL-6 promotes MSCs homing to the tumor sites in mouse xenograft models." (PMID 33472580, 2021). "Secreted from MSCs, IL-6 seems to be able to mediate a plethora of different actions, e.g. from anti-apoptotic to tumour promoting activities." (PMID 34052945, 2021). "Our previous studies demonstrated that resveratrol (RV), a nutraceutical and caloric restriction mimetic with tumor-suppressive properties, counteracts cancer cell motility induced by stromal IL-6 by upregulating autophagy." (PMID 34831435, 2021). "As a tumor driver, IL-6 promotes tumor cell proliferation, survival, angiogenesis, and evasion of immune surveillance." (PMID 34214127, 2021). "Leptin changes closely reflected changes in IL-6, according to tumor objective response or progression." (PMID 33809200, 2021). "Tumor cells produce many factors that stimulate osteolysis, such as PTHrP, IL-1, IL-6, IL-8, IL-11, and transforming growth factors, which directly inducing RANKL-mediated osteoclast differentiation and maturation." (PMID 34168981, 2021). "Knockdown of RANK or IL-6 in cancer cells, or administration of an anti-IL-6 receptor antibody reduced tumor growth in bone." (PMID 33809315, 2021). "Additional multiplex IF-IHC of CD163, CD8, PD-1 and panCK was performed on 20 tumor specimens, which were stained for Rab37, IL-6 and CD45." (PMID 34093869, 2021).
tumor (continued). "Inoculation of INA-6 cells [interleukin 6 (IL-6)–dependent human MM cell line] into SCID-hu mice resulted in tumor engraftment and burden in the implanted bone with an increase in soluble human IL-6 receptor (shuIL6R) and human IL-6 in this mouse." (PMID 34163520, 2021). "In a model for human SCC, designed by Lederle and colleagues, it has been revealed that IL-6 play a pivotal role in mediating neoplastic transformation from a benign to an invasive tumor phenotype." (PMID 33461943, 2021). "Another study in breast cancer discovered that IL-6 is significantly higher secreted by CA-MSCs than BM-MSCs, which mediates the pivotal role of CA-MSCs in enhancing the proliferation of tumor cells." (PMID 34513701, 2021). "Tumor-induced IL-6 impairs the ketogenic response to inhibit caloric intake, leading to a systemic metabolic stress response that hinders anticancer immunotherapy in PDAC." (PMID 34336821, 2021). "High tumor expression of c-Met and high basal serum levels of HGF, IL-6, CXCL11 and CXCL10 were significantly associated with reduced PFS and/or OS." (PMID 34200459, 2021). "One mice study showed IL-6 shifts macrophage polarization towards tumor-promoting, CCL-20 producing, macrophages." (PMID 34574641, 2021). "In response to TLR4 signaling in macrophages, the E2 mediated the secretion of inflammatory cytokine (IL-1β, IL-6, and TNF-α) and contributed to the tumor-associated inflammation and cancer immune escape." (PMID 34098945, 2021). "Bioinformatics analyses and functional studies demonstrated that AEG-1 silencing decreased M2-polarization of HMC3 microglia and the secretion of tumor supportive cytokines IL-6 and TGF-β1." (PMID 34462446, 2021). "Blocking of IL-6 by neutralizing antibody or statin treatment can suppress tumor progression, suggesting alteration of the TME." (PMID 34063828, 2021). "Treatment with trabectedin depleted monocytes and macrophages in several animal tumor models and resulted in reduced tumor growth, downregulation of neoangiogenesis, and production of IL-6, CCL2, and CXCL8." (PMID 33919517, 2021). "It was revealed that persistent increased IL-6 concentration, after tumor resection, had an unfavorable value in predicting the presence of distant metastases." (PMID 34441316, 2021). "In conclusion, our study described a novel mechanism, in which TDO2 mediated the Trp metabolism and activation of the Kyn/AhR/IL-6 signaling pathway in tumor cells." (PMID 34657635, 2021). "IL-6 promotes T cell migration to lymph nodes and tumor areas and can exhibit cytotoxic effects on tumor cells by activating T cells." (PMID 34267603, 2021). "IL-6/STAT3 signal axes elicit an immunosuppressive in tumor microenvironment, it is important to therapy HCC by blocking the IL-6/STAT3 signaling pathway." (PMID 34976809, 2021). "We further investigated the mechanisms of radiation resistance by measuring the expression levels of certain proteins involved in tumor proliferation- and metastasis-related pathways (IL-6/STAT3, SDF-1/CXCR4, and PI3K/AKT/mTOR)." (PMID 34539883, 2021). "Further research into the possible mechanism of IL-6-mediated tumor promotion showed that macrophage-derived IL-6 attached to a soluble IL-6R is crucial in IL-6 trans-signaling in intestinal epithelial cells and thus in the development of CAC." (PMID 34884543, 2021). "IL-6 is suggested to modulate the local tumor microenvironment and systemic immune responses contributing to the immunosuppressive environment and allow cancer cells to acquire an advanced malignant phenotype in cancer patients." (PMID 34578883, 2021). "In experimental models, HSPCs promote tumor cell proliferation, expression of the immune checkpoint PD-L1 and secretion of tumor promoting cytokines such as IL-6, IL-8 and CCL2, indicating concomitant support of both malignancy and immunosuppression." (PMID 34162860, 2021).
tumor (continued). "So far, most reports about the mechanism that the tocilizumab inhibits the tumor growth are dependent on blocking IL6 and IL6R signaling." (PMID 33576874, 2021). "On the other hand, a combination (TZB+ATV) therapy can increase the anti-tumor efficacy by decreasing the overall expression levels of IL-6, NFκB (green dashed), and Bcl-2 (red solid), and by increasing the overall BAX levels (blue circle)." (PMID 34669701, 2021). "Here, we investigated the diagnostic accuracy of selected tumor biomarkers (i.e., AFP, PIVKA-II and GPC-3); adipokines (i.e., adiponectin and leptin) and IL-6, alone or in combination, for the discrimination between patients with or without NAFLD-related HCC." (PMID 34064999, 2021). "CCL2 produced by tumor cells stimulates microglial IL-6 production, which leads to tumor growth and invasiveness." (PMID 34949203, 2021). "We identified four tumor hallmarks including Angiogenesis, IL6-JAK-STAT3 signaling, Reactive oxygen species pathway and Oxidative phosphorylation were prominently enriched in high-risk UM patients." (PMID 33682883, 2021). "The induction of IL-6 expression directly depended on the intensity of KIM-1 shedding from the tumor cell surfaces." (PMID 34603757, 2021). "It has been reported that TNF‐α or IL‐6 promotes tumour proliferation and invasion in an autocrine‐dependent manner." (PMID 33410581, 2021). "Here, our study demonstrates that IL-6 blockade partially reverses tumor immunosuppression and stimulates T-cell infiltration into GBM tumors." (PMID 34103524, 2021). "In this context, OGFRP1 is able to sequester miR-149-5p, stimulating IL-6 upregulation and promoting chemoresistance in PC tumor cells." (PMID 34868907, 2021). "For instance, cancer-associated fibroblast (CAF)-derived IL-6 interacts with the IL-6 receptor to activate STAT3 and ERK1/2 signaling pathways that promote tumor growth in gastrointestinal cancer." (PMID 33406733, 2021). "Innate immune cells of the myeloid lineage are the principal sources of the inflammatory cytokines tumor necrosis factor (TNF), interleukin 1 beta (IL-1β), and interleukin 6 (IL-6) in the tumor microenvironment (TME)." (PMID 33808059, 2021). "There is also evidence for tumor permissive effects of BM stromal cells on DLBCL cells through secretion of IL-6 and IL-17A, which promote both cell proliferation and drug resistance." (PMID 34956214, 2021). "Interleukin-6 (IL-6) is a typical tumor promoting cytokine in the interleukin-6 cytokine family, which regulates various STAT3-mediated carcinogenesis." (PMID 34384424, 2021). "For example, TGF-β, IL-6, G-CSF and interleukin 35 (IL-35) are shown to induce pro-tumor polarization of TANs." (PMID 34359674, 2021). "In glioblastoma, the tumor endothelium was shown to be the main source of IL-6 secretion, which contributes to the adoption of an anti-inflammatory and pro-tumorigenic macrophage phenotype." (PMID 34073394, 2021). "MMP2 and MMP9 production by tumor cells were described to also be controlled by adipocyte-derived leptin and IL-6 through the activation of the FAK- and Src-dependent pathways." (PMID 33917351, 2021). "Of the 13 tumor samples with high IL-6 expression, only one sample exhibited high Ang1 expression as evidenced by immunohistochemical staining." (PMID 33833265, 2021). "The production of MCP-1 in many tumor cell lines is upregulated by stimulation with IL-1, IL-6, TNF-α, or transforming growth factor-β61,62." (PMID 34570442, 2021). "IL-6 signaling has been shown to play an important role in tumor progression and metastasis dissemination in a different tumor type." (PMID 34834397, 2021). "Jagged1, by stimulating IL-6 release from osteoblasts and activating osteoclast differentiation, promotes tumor growth." (PMID 34572548, 2021). "We next sought to investigate the effect of IL-6 signaling in vivo focusing on primary tumor growth, metastasis and HSPC differentiation." (PMID 34140316, 2021).